IFIT2 (interferon induced protein with tetratricopeptide repeats 2)
Diseases named in the same sentence as IFIT2 in open-access papers (continued):
Sharing a sentence is not in itself a finding about the gene and the disease.
neurological diseases (2 papers, 2022 to 2024). "Finally, we summarize several ISGs (ISG15, IFIT2, IFITM3) that have been studied more in recent years for their antiviral infection in the CNS and their research progress in neurological diseases." (PMID 36325336, 2022). "In addition, substantial progress has been made in our understanding of individual ISGs (ISG15, IFIT2, IFITM3) in CNS viral infection and diseases in recent years, providing an essential target for the development of novel antivirals and anti-neurological disease drugs." (PMID 36325336, 2022).
Cardiovascular Disease (1 paper, 2021). "The top different expressed genes in the cardiovascular disease or MI were identified as IFIT2 and IFIT3." (PMID 34884921, 2021). "Furthermore, three potential signature genes (IFIT2, IFIT3 and IFI44L) were identified in cardiovascular disease knowledge portal." (PMID 34884921, 2021).
connective tissue diseases (1 paper, 2021). "A bioinformatics study presented that IFIT2 is a key gene to SSc-PAH and a potential biomarker, and SSc-PAH is a common PAH relevant to the connective tissue diseases." (PMID 34880909, 2021).
neurodegenerative disease (1 paper, 2020). A disorder of the central nervous system characterized by gradual and progressive loss of neural tissue and neurologic function. "While our study employs an experimental mouse system to study the role of Ifit2 in neuroinflammation and antiviral immune responses, the insights will have a long-term impact in understanding human neurodegenerative diseases, especially MS." (PMID 33253295, 2020).
IFIT2 also shares sentences with these, for which no sentence is quoted: bacterial infections (3 papers); hepatocellular carcinoma (3); dementia (2); esophageal squamous cell carcinoma (2); H1N1 virus infection (2); lung adenocarcinoma (2); oral cancer (2); primary Sjögren syndrome (2); adenocarcinoma (1); Alzheimer disease (1); amyotrophic lateral sclerosis (1); asthma (1); astrocytoma (1); Ataxia (1); autoimmune disease (1); Autoimmunity (1); B-cell lymphoma (1); bladder cancer (1); Candidiasis (1); chorioamnionitis (1); co-infection (1); colorectal (1); colorectal adenocarcinoma (1); colorectal tumor (1); Flavivirus Infections (1); glioblastoma (1); head and neck cancer (1); Hepatitis (1); hepatitis C (1); lung carcinoma (1).
A further 22 diseases each share a sentence with IFIT2 in 1 paper.